INS (insulin)
Diseases named in the same sentence as INS in open-access papers (continued):
Sharing a sentence is not in itself a finding about the gene and the disease.
diabetes (continued). "In the naïve Bayes model, the top 10 factors were the duration of diabetes, drinking status, history of hyperlipidaemia, use of insulin, education level, daily alcohol consumption, marital status, TG, duration of drinking, and duration of smoking." (PMID 34977075, 2021). "The relationship between birthweight and monogenic diabetes secondary to impaired insulin action is unclear." (PMID 33569631, 2021). "Only male sex, insulin-treated diabetes, CKD, and independent status for ADL were independently associated with unexpected death." (PMID 33670462, 2021). "LPIR, either alone or in combination with GlycA, should be explored as a non-insulin dependent predictive tool for development of insulin resistance and diabetes in youth." (PMID 34084151, 2021). "Her diabetes mellitus and hypertension also became controlled on fewer medications with ability to discontinue insulin therapy." (PMID 34321093, 2021). "PDX-1 is a transcription factor that plays a central role in β-cell function and its disruption develops diabetes with impaired expression of insulin and Glut2." (PMID 34960104, 2021). "Calcium has a vital role in the prevention of diabetes by improving insulin sensitivity and pancreatic β‐cell functions." (PMID 33747462, 2021). "However, the hallmark of this disease is insufficient insulin secretion due to β-cell loss resulting from autoimmune attack, as in type 1 diabetes (T1D), or an impairment of the β-cell function or insulin resistance built up by peripheral tissues, as in type 2 diabetes (T2D)." (PMID 33996792, 2021). "Collectively, the findings provide a comprehensive understanding of the interactions and cross-talk between the ncRNome and transcriptome in the skeletal muscle during diabetes and put forth potential therapeutic options for improving insulin sensitivity." (PMID 34190986, 2021). "Insulin resistance combined with earlier beta-cell dysfunction in this population leads to a premature insulin requirement, and higher rates of diabetes related complications (cardiovascular and renal disease), which confers greater risk of mortality." (PMID 34830706, 2021). "Of the 17 clients in the cohort who reported a previous diagnosis of diabetes, nine (53%) had an HbA1c≥6.5%, including 6 (46%) of those taking oral antidiabetic medications, and 3/5 (60%) of those taking insulin." (PMID 34813627, 2021). "Given the important role of insulin in the regulation of synaptic plasticity and the close relationship between diabetes mellitus and AD, STZ is also reported to be used in establishing AD animal models." (PMID 33732137, 2021). "Referring to former studies, diabetes-induced C57BL/6 mice administered an insulin reagent (glargine) once a day for 8 weeks showed reduced pancreatic islet size." (PMID 34358068, 2021). "It has long been known that physical activity has many health benefits—it reduces risk and slows down progression of many chronic illnesses, such as diabetes, where it improves glycemic control and insulin sensitivity in obesity." (PMID 34205752, 2021). "Further, patients treated with insulin or more complex therapeutic interventions and those experiencing diabetes-related complications excluded from the study, and thus, the conclusions cannot be generalised to a larger population." (PMID 34088897, 2021). "Climbing up the levels of care the diabetes therapy is becoming more and more complex (more insulin injections and glucose test per day as well as more diabetes technology)." (PMID 33836823, 2021). "Following CRISPR/Cas9 correction of WFS1 mutations in patients’ iPSCs, iPSC-beta cells showed dynamic glucose-stimulated insulin secretion and reversed pre-existing streptozotocin-induced diabetes after transplantation into mice." (PMID 33477961, 2021). "In individuals with diabetes caused by KCNJ11 mutations the sensitivity of these potassium channels was decreased, thereby reducing insulin secretion in the presence of glucose." (PMID 33594477, 2021).
diabetes (continued). "It is worth noting that the cutoff points for hyperglycemia and diabetes are the same for children and adults, as same as the HbA1c value, antibody titer, and insulin secretion value." (PMID 34019234, 2021). "Diabetes mellitus is a metabolic disorder characterized by hyperglycemia resulting from defects in insulin secretion, insulin action, or both." (PMID 34014991, 2021). "Diabetes only occurs when there is failure to maintain insulin secretion in the face of the increased demand." (PMID 34841432, 2021). "These patients with variants can be associated with diabetes phenotypes or clinical features involving the GCK or HNF1β gene, such as age of onset of diagnosis, level of secretion of insulin during an OGTT, or renal dysplasia or abnormality." (PMID 34746319, 2021). "Among them, 22 (6.5%) reported having been diagnosed at age 30 or earlier and to be currently using insulin, thus making their diabetes most likely type 1." (PMID 34362211, 2021). "In terms of the relationships between bile acids, glucose, insulin, and diabetes, several studies have shown interesting results." (PMID 34572086, 2021). "Combination of insulin injection and oral hypoglycemic agent had been prescribed to 28% and 13% of participants in the poor and good diabetes control respectively." (PMID 33567588, 2021). "Knowledge patients regarding diabetes mellitus and insulin therapy in Zewditu Memorial Hospital1, 2018." (PMID 33556090, 2021). "There are various kinds of drugs for type 2 diabetes mellitus such as insulin secretagogues and insulin sensitizers." (PMID 33807522, 2021). "One of the first mechanistic explanations of the hyperactivity of platelets in diabetes suggested a negative regulatory role of insulin in the ADP receptor P2Y12 and platelet function." (PMID 33946846, 2021). "Even short intermittent bouts of walking during the day reduce glucose and insulin concentrations in the postprandial period, mostly with more potent effects observed in adults with overweight to obesity and diabetes mellitus." (PMID 34444607, 2021). "Liver cirrhosis also is the strong indication for insulin treatment in persons with type 2 diabetes mellitus (T2DM)." (PMID 34118892, 2021). "Herbal remedies offered a valuable resource for pharmacological agents for diabetes even before insulin and other pharmacological drugs were discovered, and have become an increasingly important aspect of searches for curative and adjunctive treatments." (PMID 34203048, 2021). "Insulin promotes the production of the osteoblastic matrix directly and in diabetes experimental models, normoglycemia levels achieved by insulin therapy resulted in bone matrix development and osteoid production comparable to the control subjects." (PMID 34835740, 2021). "The isolation and characterization of BM-MSCs from T2DM patients in majority of published studies was performed in the context of evaluating their potentials to differentiate into insulin producing cells to reverse diabetes." (PMID 34940355, 2021). "Diabetes mellitus (DM) is a metabolic disease characterized by chronic hyperglycemia resulting from impaired insulin secretion and/or insulin resistance." (PMID 34249132, 2021). "Adherence to insulin therapy was influenced by advanced age, sex, presence of comorbidities, duration of diabetes, number of concomitant medications, adverse effects and duration of insulin therapy." (PMID 35002492, 2021). "Fasting insulin concentrations thus give erroneous estimates for β-cell function in patients with diabetes mellitus type 2." (PMID 33588833, 2021). "We have documented a new missense mutation (p.Met114Leu c.340A > C) of the NEUROD1 gene, pathogenetic for diabetes mellitus, in a 48 years-old man affected by diabetes since the age of 25 and treated with insulin basal-bolus therapy." (PMID 34654408, 2021).
diabetes (continued). "Individuals with DD were older, had longer duration of diabetes, higher HbA1c despite higher total insulin doses, more adverse lipid profile and more microalbuminuria compared to those without DD." (PMID 34530819, 2021). "A patient with Type 1 diabetes mellitus incurred annual insulin costs of $5,705, on average, in 2016." (PMID 34332631, 2021). "In the hyperglycemic environment, the increase in NLRP3 inflammasome-dependent IL-1β secretion leads to the dysfunction of insulin secretion of β cells, promotes obesity and insulin resistance, and eventually leads to diabetes." (PMID 33937267, 2021). "Zn plays a key role in the synthesis and action of insulin both physiologically and in the pathologic state of diabetes." (PMID 33572627, 2021). "Diabetes mellitus is defined as a metabolic disease related to hyperglycemia, and it results from insulin resistance or problems with insulin action or insulin secretion." (PMID 34959992, 2021). "It's also noticed that in both diseases: Alzheimer's disease and diabetes mellitus, there is evidence of decreased insulin levels in the brain compared to normal people." (PMID 34877187, 2021). "The insulin subgroup and matched reference group were comparable regarding sex, age, diabetes duration and BMI." (PMID 33855214, 2021). "Initiating insulin therapy with a basal insulin analogue has become a standard of care in the treatment of type 2 diabetes mellitus (T2DM)." (PMID 33098260, 2021). "Diabetic ketoacidosis (DKA) is a potentially life-threatening condition that occurs in patients with diabetes mellitus (DM) where the decrease in the insulin level leads to a state of metabolic acidosis and hyperglycemia." (PMID 35018256, 2021). "As the proband was first diagnosed with diabetes at the age of 23 and treated with insulin and oral hypoglycemic agents, it was crucial to identify which type of diabetes the proband had." (PMID 33604390, 2021). "Insulin stimulates transcription of malic enzyme in the liver and situations of insulin resistance or diabetes reduce G6PD activity." (PMID 33800837, 2021). "For example, children with type 1 diabetes, persons with brittle diabetes, and those with very low dose requirements of insulin need a pen device that will deliver insulin in smaller increments such as 0.5 units." (PMID 34924015, 2021). "We highlight the role of lipids in multiple regulatory steps in insulin granule biogenesis and release and also discuss how defects in granule biogenesis and release contribute to diabetes development." (PMID 33146746, 2021). "All forms of diabetes mellitus are characterized by the dysfunction and reduction of insulin-producing β-cells." (PMID 34201511, 2021). "On the opposite side of the regression tree, patients treated with insulin and having family history of diabetes represented the subgroup with the highest prevalence (40.7%) and the highest risk of dysglycemia (OR = 5.57; 95%CI 3.60–8.63)." (PMID 33842997, 2021). "The authors also demonstrate that the insulin-producing cells of corrected patient hiPSCs protect mice from diabetes, providing a proof-of-principle study for the use of replacement therapy as a treatment for monogenic diabetes." (PMID 34295307, 2021). "This analysis of healthcare claims data using clustering methodologies identified meaningful subgroups of patients with diabetes using insulin." (PMID 34238287, 2021). "Here, we found that the ER stress sensor inositol-requiring enzyme 1α (IRE1α) was activated in the Akita mice, a mouse model of mutant insulin gene-induced diabetes of youth (MIDY), a monogenic diabetes." (PMID 34675883, 2021). "In the current mouse model of diabetic peripheral neuropathy induced by STZ, β-islet cells, which mimic insulin-dependent and obesity-independent diabetes, were destroyed." (PMID 34172832, 2021).
diabetes (continued). "In general, a high burden of diabetes management is present on a daily basis despite advancements in self-management techniques for example, home use glucometers, glucose sensors and insulin pumps." (PMID 35222594, 2021). "A marked decrease in islet insulin content is seen after week 12 and, after a median period of 18 weeks, diabetes develops in most female mice." (PMID 33868170, 2021). "Early CVD factors are present in youth with type 1 diabetes despite their shorter duration of diabetes, also believed to be related to their decreased insulin sensitivity." (PMID 33828529, 2021). "The treatment used for diabetes by most of the participants was injected insulin, while some take medication and control their diets." (PMID 34360314, 2021). "Increased and decreased levels of insulin and glucose, respectively, were observed in the blood when the Ins-TCNPs were orally administered in the diabetes-induced rats." (PMID 34502560, 2021). "(c) In diabetes mellitus type 1 insufficient endogenous insulin secretion leads to upregulated gluconeogenesis." (PMID 33473341, 2021). "In the future, there will be more situations like this where AI-based medical devices replace diabetes specialists in terms of fine-tuning insulin therapy." (PMID 34902070, 2021). "Diabetes is a chronic disease resulted from insufficient insulin produced by the pancreas or due to ineffective function of produced insulin." (PMID 35155528, 2021). "VAMP2 and Cdc42 localize together at the plasma membrane and on insulin secretory granules in β-cells and play vital functions in insulin secretion and development of diabetes." (PMID 34394002, 2021). "Around 90–95% of the diabetics have type 2 diabetes mellitus (T2DM) that is characterized by insufficient insulin secretion by pancreatic β-cells, which leads to insulin resistance." (PMID 34692767, 2021). "Our study indicates a shift in the era of diabetes probably due to the more extensive use of modern equipment in glucose-lowering therapy, such as advanced insulin pumps and continuous glucose monitoring devices." (PMID 34494137, 2021). "Recurrent hypoglycaemia (RH) is a major side-effect of intensive insulin therapy for people with diabetes." (PMID 34122346, 2021). "Diabetes significantly increased the rapidity of FI increase, congruent with recent research, which highlights the critical role of insulin resistance and Insulin-like Growth Factor-1 in the development of frailty." (PMID 34922488, 2021). "Work is ongoing to identify the peptide that triggers immune response in diabetes—a number of candidates including autoantigens such as insulin are under investigation." (PMID 33558538, 2021). "The patients had diabetes with 100% using insulin therapy, and 100% of patients had Wagner-Meggitt’s grade 3 lesions (deep ulcer with abscess or osteomyelitis)." (PMID 34444735, 2021). "As it is 100 years since the discovery of insulin, what do you think has been the most significant discovery in diabetes research since then?" (PMID 34762125, 2021). "Diabetes elevated the relative abundance of phylum Actinobacteria, which was regulated oppositely by the treatment of metformin or insulin." (PMID 35046817, 2021). "Type 2 diabetes mellitus (T2DM) is linked to insulin resistance and a loss of insulin sensitivity, leading to millions of deaths worldwide each year." (PMID 34299620, 2021). "Diabetes mellitus refers to high blood sugar by through of insulin or resistance against insulin-sensitive organs." (PMID 34575960, 2021). "These drugs provided an opportunity to address and directly reverse, at least in part, the defects in insulin action seen in individuals with type 2 diabetes mellitus." (PMID 34680546, 2021). "Whereas the hypoglycemic activity of oleanolic acid is carried out by improving the insulin response, it maintains the function and survival of β-cells and prevents complications of diabetes." (PMID 33567795, 2021).
diabetes (continued). "Insulin‐mediated glucose uptake has been found to be reduced by more than 50% in patients with type 2 diabetes mellitus, which is related to specific alterations in the insulin signal transduction pathway, such as the PI3K/AKT and AMPK signalling pathways." (PMID 34136157, 2021). "Alloxan induces diabetes by killing the pancreatic insulin-secreting cells, resulting in hypoinsulinemia and hyperglycemia." (PMID 34249266, 2021). "For diabetes, specific characteristics are particularly relevant (e.g., size and distribution of β cells, similarity in insulin structure) that make the pig a valuable model for human glucose metabolism." (PMID 34946940, 2021). "Clinical experience finds that a low carbohydrate diet (LCD) can be effective for all forms of diabetes mellitus, including T2D, and those characterized by a low insulin state such as Type 1 Diabetes." (PMID 34434951, 2021). "Regarding diabetes, greatest variation was seen regarding insulin controlled gestational diabetes, with units split on IOL at 38+ versus 39+ weeks, and pre-existing diabetes (both Type I and Type II), with units split across IOL at 37+, 38+ and 39+ weeks." (PMID 34016068, 2021). "Insulin resistance is one of the earliest manifestations of diabetes, and it refers to reduced sensitivity and response to insulin in target tissues, including the liver, skeletal muscle, and adipose tissue." (PMID 34564163, 2021). "For these children in Germany, insulin pump therapy is often initiated during the first hospitalization, immediately after the diagnosis of diabetes is made." (PMID 33258970, 2021). "Type 2 diabetes mellitus (T2DM) is a chronic metabolic disorder characterized by reduced insulin sensitivity, followed by a compensatory increase in insulin secretion." (PMID 34012420, 2021). "Drosophila is used to study diabetes because it has a very similar insulin pathway to that of humans." (PMID 33484713, 2021). "We trained BCAUS on the diabetes dataset setting Insulin (the most common treatment in the dataset) as control and comparing all other drug combinations against this control." (PMID 34544367, 2021). "In the present study, we investigated the effects of metformin on gut microbiota and metabolome profiles in serum and compared it with insulin treatment in rats with type 2 diabetes mellitus (T2DM)." (PMID 35046817, 2021). "Stem cells derived from hESCs or iPSCs, can be differentiated into mature insulin producing islet cell clusters capable of fully reversing diabetes in mice and rats." (PMID 33573247, 2021). "Pancreatic β-cells, which produce insulin, become dysfunctional and dedifferentiate during diabetes progression." (PMID 34436451, 2021). "Assessment tools on mobile platforms have the ability to capture multiple aspects of dietary behavior in real-time throughout the day to inform and improve diabetes management and insulin dosing." (PMID 33918343, 2021). "SIRT3 in skeletal muscles regulates oxidative stress, insulin resistance, and energy homeostasis, especially in type 2 diabetes mellitus." (PMID 33614337, 2021). "For instance, insulin can delay the development of diabetes via modulation of microbiota homeostasis." (PMID 34445047, 2021). "In chronic metabolic states that present as obesity and diabetes, tissues, including adipose tissue and skeletal muscle, become unresponsive to insulin." (PMID 34299261, 2021). "In a study showing long-term success for diabetes management, the intervention was multi-modal; tailored and interactive text messaging, self-monitoring relating to use of insulin, and ability to contact a health care provider." (PMID 34418987, 2021). "Gauthier and Wollheim’s24 study on the pathogenesis of diabetes mellitus found that the amount of insulin released by pancreatic β cells depended on the exocytosis of protein granules secreted by pancreatic β cells in the calcium-dependent pathway." (PMID 31868832, 2021).